IL6 (interleukin 6)
Diseases named in the same sentence as IL6 in open-access papers (continued):
Sharing a sentence is not in itself a finding about the gene and the disease.
heart disease (102 papers, 2007 to 2025). "IL-6 is considered to be a part of the inflammatory response and its increase is associated with increased risk of heart diseases." (PMID 41295638, 2025). "Theassociation between high-risk characteristics, adverse cardiovascular outcomesand IL-6 supports its potential target role as therapeutic strategy in patientswith acute ischaemic heart disease." (PMID 39076483, 2024). "As a marker of systemic inflammation, IL-6 can help assess the degree of inflammation and cardiovascular risk in individuals with heart disease." (PMID 39273041, 2024). "High-frequency keywords in the field of IL-6 signaling pathway in mendelian randomization included mendelian randomization, interleukin-6, il-6, c-reactive protein, association, coronary-heart-disease, inflammation, instruments, risk, and so on." (PMID 38579070, 2024). "IL-6, an important mediator of inflammation with a causal role in heart disease, was among the top biomarkers for CV death in the present study." (PMID 34358298, 2022). "Psychological stress, featured with increased IL-6, is a confirmed risk factor in people with heart diseases." (PMID 35747434, 2022). "Cong Lin-Liu and colleagues showed an inversely proportional association between IL-6 and ischaemic heart disease (both acute and chronic ischaemic syndromes)." (PMID 36013520, 2022). "Outside the context of endurance exercise, some studies have reported an association between increased levels of IL-6 and cardiac disease." (PMID 26070197, 2015). "The interleukin (IL)-6 is known as a pleiotypic factor that has been associated with various cardiac diseases." (PMID 21785627, 2011). "Elevated inflammatory markers like CRP and IL-6 highlight the inflammatory bridge between poor OH and heart disease." (PMID 40722588, 2025). "IL-6 is a pleiotropic cytokine (downstream of IL-1β action) and is a powerful predictor of the severity of heart disease." (PMID 39063055, 2024). "In conclusion, all of these results show the harmful effect of IL-6 on the immune system in heart disease." (PMID 37047468, 2023). "In this review, the pathophysiological effects of interleukins including the IL-1 family (IL-1, IL-18, IL-33, and IL-37), IL-2, IL-4, the IL-6 family (IL-6 and IL-11), IL-8, IL-10, and IL-17 on primary cell types of heart disease is elucidated." (PMID 37047468, 2023). "Consistently, RNA-seq analysis revealed that key cardiac disease-related signaling pathways, including TGFβ, IL6, Renin-Angiotensin, and NFAT, were blunted in SIRT5OE TAC mice." (PMID 35851833, 2022). "Although the precise contribution of IL-6 to cardiac diseases remained controversial for several years, a more recent study demonstrated that IL-6 knockout prevented cardiac remodeling and dysfunction in mice subjected to transverse aortic constriction (TAC)." (PMID 34494646, 2021). "The role of IL‐6 in the pathogenesis of cardiac disease is well established in experimental models and in humans." (PMID 34773379, 2021). "Several inflammatory cytokines, such as TNFα, the IL-1 family, IL-6, IL-8, IL-10, IL-18, and IFNα have also been shown to play a pathological role in various heart diseases." (PMID 35069538, 2021). "Pro-inflammatory cytokines such as TNF-α, IL-1β and IL-6 and inflammatory mediators like NF-kB were considerably boosted during the cardiac disease and similar momentum was observed in the disease control group mice." (PMID 32762480, 2020). "This new model provides potential therapeutic targets for intervention in the heme response and IL-6 pathways to prevent cardiac disease in SCD that merit additional investigation." (PMID 32973791, 2020). "As proinflammatory/profibrotic mediators are also augmented in cardiac disease, the effect of a range of proteins, including Ang II, TGFβ1, IL-1β, IL-1α, TNFα, IL-6 and IL-6 in combination with the sIL-6R on Cx43 mRNA expression was examined in CFs." (PMID 31909243, 2020).
heart disease (continued). "The wild genotypes of the IL6 and IL8 gene polymorphisms were present at a high frequency and with elevated CRP expression and proved to be good predictors of heart disease." (PMID 30804931, 2019). "Inflammatory markers, including high-sensitivity C-reactive protein (hsCRP), interleukin 6 (IL-6), and D-dimer, are strong predictors of cardiac disease and mortality in HIV-infected patients with known CVD." (PMID 30363715, 2018). "Remarkably, disruption of the expression of IL-6 was shown to be beneficial against fibrotic heart disease." (PMID 26972749, 2016). "In another type of cardiac disease; experimental autoimmune myocarditis (EAM), the IL-6/IL-17 response seems to be pathogenic." (PMID 23776551, 2013). "IL-6 is an important cytokine in the innate immune response, and has been found to be elevated in such diverse conditions as suicidal depression and heart disease." (PMID 23082161, 2012). "We analyzed PM effect on cytokine levels in 21 individuals with known cardiac disease by pairing 59 repeated-measures of endothelin-1, IL-6 and IL-6 receptor, TNF-α and TNF-α receptors [p55, p75], and MCP-1 to outdoor residence level measures of PM." (PMID 17270049, 2007). "IL-6 is a powerful predictor of the severity of heart disease." (PMID 39063055, 2024). "This review will primarily focus on the pathophysiological effects of various interleukins including the IL-1 family (IL-1, IL-18, IL-33, IL-37), IL-2, IL-4, the IL-6 family (IL-6 and IL-11), IL-8, IL-10, IL-17 on primary cells of heart disease-CMs, FBs, ECs, and immune cells." (PMID 37047468, 2023). "In an array of heart diseases, IL-6 promotes fibroblast proliferation and stimulates ECM synthesis." (PMID 37047468, 2023). "We also investigated whether IL-6 and TNF-α predict all-cause morbidity, cardiac disease, and all-cause mortality in gorillas and found that cardiac disease was best predicted by lower TNF-α alongside age and sex." (PMID 36230446, 2022). "Considering the coexistence of oxidative stress and inflammation in various cardiac diseases, we investigated the ability of the IL-6 inhibitor to restore altered cardiomyocyte stiffness at higher sarcomere lengths and found comparable results upon the treatment." (PMID 36358581, 2022). "IL-6 has emerged as a promising biomarker and potential target in the development of heart disease." (PMID 35163735, 2022). "Besides hs-CPR and IL-6, studies revealed that cardiac diseases are highly related to other inflammatory factors, such as increased oxidative stress, procoagulant activity, and adhesion molecules." (PMID 33506051, 2021). "These new observations provide the basis for a previously unknown heme/IL-6 axis in the development of cardiac disease in patients with SCD." (PMID 32973791, 2020). "In conclusion, our network meta-analysis showed that long-term using statins reduced inflammatory factors including CRP and IL-6, increased lung function index including FEV1% and FEV1/FVC%, and reduced the risk of AECOPD, heart disease-related mortality and all-cause mortality." (PMID 30674312, 2019). "With this programmable platform, the initial application of chip-based multianalyte detection systems for cardiac applications was completed by targeting two inflammatory biomarkers, C-reactive protein (CRP) and interleukin-6 (IL-6), both relevant to the cardiac disease cascade." (PMID 30995728, 2019). "IL-6 is a pro-inflammatory cytokine that is upregulated in various cardiac diseases." (PMID 26972749, 2016). "In contrast, IL-6 signaling seems to be protective in acute cardiac diseases." (PMID 26972749, 2016). "Moreover, we postulated that endothelin-1 and IL-6 levels would be elevated on high air pollution exposure days in individuals with pre-existing heart disease." (PMID 17270049, 2007).
heart disease (continued). "In cardiac diseases, RECK has been shown to reduce several downstream effectors of Angiotensin II (Ang-II), such as Interleukin-6 (IL-6)/IL-6 receptor (IL-6R)/glycoprotein 130 (IL-6 signal transducer) signaling." (PMID 38139236, 2023). "No prior publications have investigated any potential linkage between IL-6 and hemolysis in mice and patients with SCD, particularly in cardiac disease." (PMID 32973791, 2020). "In studies of lung and heart disease, iloprost either decreases or does not affect IL‐6; however, in short‐term PCLS experiments, we previously found increased IL‐6 with iloprost treatment." (PMID 40650429, 2025). "Systemically high levels of IL-6 produced by PBMC in HF patients affect NK cells through signal transduction pathways and may also affect other cells involved in heart disease, including cardiomyocytes, and possibly the function of other immune cells." (PMID 37047468, 2023). "In CD, IFN-γ, IL-2, IL-6, IL-10, IL-12, and IL-17 are proposed as surrogate markers of cardiac disease (versus no disease) (9, –, 14)." (PMID 34479416, 2021). "However, when the expression of IL-6, MCP-1, and CCR2 was evaluated, we found that only PBMC from patients with heart disease displayed significantly increased levels of these cytokines in comparison with healthy individuals." (PMID 35360222, 2021). "Moreover, another research identified the down-regulation of IL-6 and TNF-α as a sign of amelioration of heart disease." (PMID 34526481, 2021). "Moreover, they had lower levels of lymphocyte count, albumin, EGFR, and TBIL, and higher levels of SBP, cardiac biomarkers (Hs-TnI, CK-MB, Myo, and NT-proBNP), WBC, neutrophil, inflammatory factors (Hs-CRP, IL-2R, IL-6, IL-8, and TNFα) and D-dimer in comparison to survivors without cardiac disease." (PMID 33553255, 2020). "Despite a great amount of preliminary preclinical data in cardiac diseases, the therapeutic use of anti-IL1 agents (as anakinra or rilonacept) have never been reported in SSc-pHI, and no large trials to support anti-IL6 therapy with tocilizumab have been performed." (PMID 39015843, 2024).
respiratory diseases (89 papers, 2011 to 2025). "Vitamin C and zinc modulate oxinflammation, combating reactive oxygen species and reducing the expression of TNF-α and IL-6, inflammatory cytokines associated with respiratory disease progression and PACS." (PMID 40161300, 2025). "Elevated IL-6 levels have been associated with various inflammatory diseases, including respiratory disorders." (PMID 39596850, 2024). "Interleukin-6 (IL6) is crucial in regulating the inflammatory cascade, but the causal link between IL6 signaling downregulation and respiratory diseases risk is unclear." (PMID 38898459, 2024). "Upregulation of IL-6 concentrations is associated with increased inflammation, which can contribute to respiratory diseases and other health issues." (PMID 38797836, 2024). "Studies on the association between DII and respiratory diseases are rare with IL-6 and forced expiratory volume 1 (FEV1) levels, suggesting a relationship between an inflammation-inducing diet and impaired lung function." (PMID 35685606, 2022). "However, the causal relationship between the downregulation of the IL6 signaling pathway and the risk of multiple respiratory diseases remains uncertain." (PMID 38898459, 2024). "It has been reported that disruption of the redox balance by CS leads to the production of proinflammatory cytokines, i.e., IL-1β, IL-6, IL-8, and TNFα in smokers, regulation of which is closely associated with the progression of respiratory diseases, such as COPD." (PMID 33660061, 2021). "IL-6 was also positively correlated with dyspnea, which may represent, under the point of view of the pathophysiology, the intensity of the lung’s inflammatory process, which is associated with respiratory disease severity." (PMID 27905908, 2016). "A critical aspect of this study was the assessment of inflammatory cytokines, specifically IL-6 and IL-1β, which are well-established mediators of acute and chronic inflammation in respiratory diseases." (PMID 40218944, 2025). "CXCL9, CCL2, IL6, CXCL10, and IL8 have been linked to various respiratory diseases and retain sensitivity for their level estimates as well." (PMID 40650062, 2025). "Dupilumab has demonstrated efficacy in decreasing IL-6 concentrations in nasal fluid among individuals with aspirin-exacerbated respiratory disease (AERD)." (PMID 41155381, 2025). "Here, it was shown that the administration of 10 μM 1,8-cineol, which is successfully used as a drug component against human respiratory diseases, reduced LPS-induced IL-6 secretion in isolated human monocytes by 76 ± 10%." (PMID 38388989, 2024). "The multifunctional inflammatory cytokine TNF-α, which is known for its capacity to stimulate the IL-1β and IL-6 release, emerges as a pivotal player in the pathogenesis of respiratory disorders within lung injury models." (PMID 39596850, 2024). "Uncontrolled levels of IL-6 can worsen lung inflammation and contribute to the progression of respiratory disorders." (PMID 39867697, 2024). "Pro-inflammatory cytokines, such as IL-1β, TNF-α, and IL-6, were quantified in the serum due to their crucial roles in initiating and sustaining inflammatory responses, particularly in respiratory disorders." (PMID 39596850, 2024). "IL-6 has a short half-life and inter-individual variability, and its association with risk for CVD and respiratory diseases is still controversial." (PMID 36991369, 2023). "High prevalence of SARS-CoV-2 plasma viral load was found related to increased respiratory disease severity, low lymphocyte counts, and increased inflammation markers such as C-reactive protein and interleukin (IL)-6." (PMID 35582503, 2022). "Tumour necrosis factor alpha (TNF-α), transforming growth factor-β (TGF-β), interleukin-1 (IL-1) and interleukin-6 (IL-6) are well-known biomarkers of proinflammatory cytokines, which have also been found to be increased in respiratory disease." (PMID 36367996, 2022).
respiratory diseases (continued). "Increased IL-6 expression, as seen in the cytokine storm brought about by many respiratory diseases, results in downregulated HLA-DR expression on human monocyte-derived DCs through the IL-6 mediated STAT3 pathway." (PMID 34452063, 2021). "Exposure to cold conditions induces tracheal contraction or increases inflammatory indicator concentrations in plasma, such as interleukin-6 (IL-6) or norepinephrine, which induces respiratory diseases." (PMID 34063510, 2021). "We highlight the potential of IL-6 inhibitors to prevent the progression of respiratory disease to a point requiring ventilator support." (PMID 32635353, 2020). "These cells were removed from natural biological influences of hormones and grown for 2–3 months in vitro, indicating an intrinsic mechanism contributes to the sexually dimorphic production of IL‐6 in respiratory disease." (PMID 32472750, 2020). "We present, for the first time, in vitro evidence supporting clinical findings of differential production of IL‐6 between males and females across various respiratory diseases." (PMID 32472750, 2020). "Among them, representative respiratory diseases-related targets included IL-6, IL-10, IL-1β, TNF-α, interferon (IFN)-γ, epidermal growth factor (EGF) and its receptor (EGFR), TNF-α, transforming growth factor (TGF)-β1, etc." (PMID 31530860, 2019). "Conversely, in 2015, IL-6 was shown to be able to activated PYK2 in the context of respiratory diseases." (PMID 29455640, 2018). "IL6 is a well-known marker of diesel and airborne PM exposure, and it has been already suggested to contribute to particles-induced cardiovascular and respiratory diseases.." (PMID 29703138, 2018). "Proinflammatory cytokines, like TNF-α, IL-1β, and IL-6, by neutrophils are produced, which have close links with respiratory diseases." (PMID 29483931, 2018). "Elevated TNF-α and IL-6 levels can contribute to virus-mediated respiratory diseases or acute lung injury." (PMID 30105014, 2018). "This study found increased levels of VEGF and IL-6 in serum samples of active PTB patients compared to those with other respiratory diseases." (PMID 28859607, 2017). "Increasing data suggest that azithromycin suppresses the production of inflammatory cytokines such as TNF-α, IL-1β, IL-6 and macrophage inflammatory protein 2 apart from the antibiotic effect not only in respiratory diseases but also in genital infections." (PMID 25174641, 2014). "The concentrations of further soluble blood markers such as CC16, a marker of respiratory diseases and the inflammatory markers IL-6 and IL-8 were also similar in both groups." (PMID 24340055, 2013). "This study confirms that the TCM compound MBFD significantly enhances average daily weight gain in calves, elevates serum immunoglobulin levels (IgG, IgM), and reduces both respiratory disease incidence and pro-inflammatory cytokine levels (IL-6, TNF-α, IL-1β)." (PMID 41234407, 2025). "Related to respiratory disease, factor B can be synthesized and secreted by alveolar type II pneumocytes, polymorphonuclear cells, and alveolar M1 macrophages and further induced by local or systemic IL-1, IL-6, TNF-α, and/or IFN-γ activity." (PMID 39346910, 2024). "TNF-α and IL-6 are the key contributors to IAV-mediated respiratory diseases and acute lung injury." (PMID 30105014, 2018). "Various cytokines, such as IL2, IL4, IL6, IL8, and TNFα, and other inflammatory markers, such as intercellular adhesion molecule (ICAM) 1, soluble P-selectin, and CRP, have previously been associated with metal exposure or respiratory diseases." (PMID 25272992, 2014).